SON (SON DNA and RNA binding protein)
Diseases named in the same sentence as SON in open-access papers (continued):
Sharing a sentence is not in itself a finding about the gene and the disease.
myeloproliferative disorder (1 paper, 2024). A clonal hematopoietic stem cell disorder, characterized by proliferation in the bone marrow of one or more of the myeloid (i.e., granulocytic, erythroid, megakaryocytic, and mast cell) lineages. "Furthermore, dysregulation of XIST, RUNX1, SON, ERG and STAT1 was observed, contributing to myeloproliferative disorders." (PMID 38474215, 2024).
osteosarcoma (1 paper, 2023). A usually aggressive malignant bone-forming mesenchymal neoplasm, predominantly affecting adolescents and young adults. "Keratinocyte nuclei showed signals of the nuclear speckles marker SON, forming cloud-like accumulations in the confocal images similarly to the cultured human osteosarcoma U2OS cell line." (PMID 37484912, 2023).
pancreatic cancer (1 paper, 2015). "Knockdown of SON in cultured pancreatic cancer cells caused G2/M arrest and apoptosis." (PMID 25699241, 2015). "By using a subcutaneous xenograft model in immunocompromised mice, pancreatic cancer cells with knockdown of SON resulted in a significant reduction in in vivo tumorigenesis." (PMID 25699241, 2015).
cancer (10 papers, 2007 to 2024). A tumor composed of atypical neoplastic, often pleomorphic cells that invade other tissues. "SON is required for microtubule dynamics, spindle pool separation during mitosis, and the proliferation of epithelial cells, and it is further linked to poor cancer prognosis." (PMID 39796712, 2024). "Taken together, this suggests SON, FUS, and ALDHA3 can be potential targets for the treatment of cancer-associated EMT." (PMID 39796712, 2024). "Proteins SOX5, SON, and OLR1 have been implicated in various aspects of cancer progression and metastasis." (PMID 38003292, 2023). "In CRC, the nuclear localization of FAM83H was present in a minor population of cancers, but its localization to nuclei has been suggested to be involved in cancer progression with the interaction of SON and casein kinase 1α." (PMID 35885485, 2022). "Of special interest are the pre-mRNAs encoding AZIN1, BLCAP, SON and GLI1, all of which display dysregulation in various cancer types." (PMID 34882682, 2021). "Our finding on the SON function in intron removal from the PTBP1 transcript suggests potential roles of SON in removing detained introns from many other transcripts, thereby promoting cancer cell growth." (PMID 34548489, 2021).
infection (4 papers, 2021 to 2025). The state of being infected such as from the introduction of a foreign agent such as serum, vaccine, antigenic substance or organism. "SON (chr21:33,550,969) also showed a decreased editing level in the limbus and sclera upon infection." (PMID 38693480, 2024). "When we continued in vitro culturing of part of the GSCs used for intracranial injection, we observed an accumulation of SON shRNA-expressing GSCs at the G2/M phase of cell cycle 72 and 96 h after shRNA infection, indicating G2/M cell cycle arrest." (PMID 34548489, 2021).
tumor (4 papers, 2019 to 2025). "Collectively, these data demonstrate that PTBP1-mediated exon skipping events, which generate splice products closely associated with poor differentiation and tumor progression, can be efficiently attenuated by SON knockdown." (PMID 34548489, 2021). "From immunostaining of the tumor areas in the brain sections, we found that both SON expression and PTBP1 expression levels are significantly downregulated in tumors formed by SON shRNA-expressing GSCs, consistent with our in vitro data." (PMID 34548489, 2021). "To examine the effect of SON knockdown on GBM tumor formation and growth in vivo, we implanted SON shRNA-expressing GSC#83 and control GSC#83 cells into immunocompromised mice intracranially to generate orthotopic xenografts." (PMID 34548489, 2021). "Taken together, our data demonstrated that SON knockdown in GSCs inhibits tumor growth and reduces stemness in vivo." (PMID 34548489, 2021). "Additionally, it interacts with nuclear speckle components (e.g., SON protein) to regulate the phosphorylation status of SR family splicing factors, thereby influencing alternative splicing patterns in tumor cells." (PMID 40958861, 2025). "Importantly, we also found that SOX2, a well-known GBM cell stemness marker, is almost undetectable in the SON shRNA-expressing tumor section while control tumors showed robust SOX2 expression." (PMID 34548489, 2021). "ALPL, APOL6, SON, and VWF proteins were significantly differentially expressed between normal and tumor tissues." (PMID 35991564, 2022). "SON knockdown inhibits proliferation and clonogenicity of GBM cells in vitro and significantly suppresses tumor growth in orthotopic xenografts in vivo." (PMID 34548489, 2021). "In particular, ALPL, APOL6, SON, and VWF were lowly expressed in tumor tissues." (PMID 35991564, 2022). "Notably, the expression of 4 of these genes (TERT, ADPRM, SON and KRT32) were significantly higher in tumor tissues expressing chimeric transcripts compared to tissues without the fusion transcripts (bottom bar graphs)." (PMID 31429776, 2019). "Our GBM orthotopic xenografts also confirmed that SON reduction in GSCs leads to depletion of PTBP1 as well as the well-known GBM stemness marker SOX2, suggesting targeting SON efficiently suppresses the tumorigenic ability of GSCs and inhibits tumor cells’ stemness in vivo." (PMID 34548489, 2021).
genetic disease (1 paper, 2024). "The pathogenic effect of SON LoF variants on causing this complex human genetic disease was first reported in 2016 by our group and others." (PMID 38290089, 2024).
SON also shares sentences with these, for which no sentence is quoted: developmental delay (6 papers); breast cancer (2); COVID-19 (2); neurodevelopmental disorder (2); 21q deletion syndrome (1); acute coronary syndrome (1); anaplastic oligodendroglioma (1); ataxia telangiectasia (1); atherosclerosis (1); Fanconi anemia (1); glioma (1); heart failure (1); hematologic malignancies (1); holoprosencephaly (1); HyperIgE syndrome (1); influenza (1); lung carcinoma (1); lung disease (1); malignant brain tumors (1); myeloid malignancies (1); neurodegenerative disease (1); ovarian serous cystadenocarcinoma (1); psoriasis (1); schizophrenia (1); substance abuse (1); Thrombocytopenia (1).